IL2 (interleukin 2)
Diseases named in the same sentence as IL2 in open-access papers (continued):
Sharing a sentence is not in itself a finding about the gene and the disease.
melanoma (continued). "For instance, in a phase 3 randomized trial, patients with advanced melanoma treated with the gp100 peptide vaccine and interleukin-2 showed a significantly higher overall clinical response rate (16% vs. 6%) and longer PFS (2.2 vs. 1.6 months) compared to those receiving interleukin-2 alone." (PMID 39204073, 2024). "Despite its widespread use in the treatment of advanced KC and melanoma, the therapeutic efficacy of IL-2 remains limited, and it may be accompanied by severe side effects." (PMID 39267764, 2024). "Moreover, when combined with the immune checkpoint blocker nivolumab, IL-2 significantly inhibits tumor growth in cancers such as melanoma, RCC, NSCLC, uroepithelial carcinoma, and triple-negative breast cancer (TNBC)." (PMID 38928150, 2024). "However, only two cytokines have received FDA (Federal Drug Administration) approval as single anti-cancer agents so far: IFN-alpha for Stage III melanoma adjuvant therapy and IL-2 for metastatic melanoma and RCC." (PMID 38360737, 2024). "Specifically, objective response rate (ORR) values of over 20% have been observed with HD IL2 monotherapy in immune-checkpoint inhibitor (ICI) failed melanoma and renal cell carcinoma (RCC) patients, comparable with historical response rates in ICI-naive patients." (PMID 38563906, 2024). "Similarly, exosomes derived from engineered Jurkat T cells expressing IL-2 on their surface were shown to reprogram miRNA levels, suppress PD-L1 expression in melanoma cells, and inhibit tumor growth in immunocompetent mouse models." (PMID 39724442, 2024). "The use of interleukin-2 (IL-2), a T-cell growth factor, has enabled large-scale in vitro expansion of TILs and demonstrated increased lethality against tumor cells in conditions such as melanoma, HCC, lung carcinoma, ovarian cancer, and other solid tumors." (PMID 38928150, 2024). "Higher expression of Th1-associated genes, such as tumor necrosis factor-alpha (TNF-α) and IL-2, was detected in 20 primary melanoma tumors that spontaneously regressed, indicating activation of the host antitumor immune response, compared with non-regressing tumors." (PMID 39273452, 2024). "In another clinical trial, a DNA vaccine encoding gp100 was administered in patients with stage IV melanoma with or without intradermal injection of IL-2, the results of which have been equivocal." (PMID 39872522, 2024). "It is well known that IL-2 is active in metastatic renal cell cancer and melanoma." (PMID 39764216, 2024). "In addition, Katarina M studied the in vitro effects of IL-12 combined with interleukin-2 (IL-2), which has been used for decades in the treatment of melanoma, on the function and receptor expression of NK cells and their subsets." (PMID 38753073, 2024). "Recent reports of modifications to the IL-2 approach are promising for melanoma treatment." (PMID 38399429, 2024). "However, in a phase II trial, subcutaneous injections of low-dose IL-2 (125000 IU/kg/day) were administered to patients with advanced melanoma using TIL therapy." (PMID 39081713, 2024). "Lifileucel (LN-144), a one-time autologous TIL therapy developed by Iovance Biotherapeutics, demonstrated an ORR of 31.4%, with 8 CRs and 40 PRs following a single infusion and up to six doses of HD IL-2 in a phase II C-144-01 trial of 153 patients with heavily pretreated advanced melanoma." (PMID 39114660, 2024). "IL-2 has previously been used as an immunotherapeutic agent for melanoma in the United States." (PMID 39728976, 2024). "In addition, maltol enhanced T cell-regulated melanoma cell eradication with an increase in IL-2 production." (PMID 37731735, 2023). "The authors of this report speculate that increased expression of EZH2 during melanoma immunotherapy with anti-CTLA-4 antibodies or IL-2 triggers diminution of therapy efficacy." (PMID 37325482, 2023).
melanoma (continued). "To determine whether ∆Ex3PD1 could reduce T cell exhaustion, we measured IL-2 mRNA in T cells expressing ∆Ex3PD1 after co-incubation of the T cells with IFN-γ-stimulated MM418 melanoma cells (expressing PD-L1)." (PMID 37973660, 2023). "High-dose interleukin-2 (IL-2) therapy, approved for advanced melanoma and renal cell carcinoma in 1998, demonstrated some activity in pretreated pediatric sarcoma, though its use was restricted due to the high incidence of severe toxicity (cytokine-induced capillary leak syndrome)." (PMID 37190214, 2023). "Also, when tested in a clinical setting that includes a 14-day rapid expansion procedure in the presence of irradiated feeder cells, anti-CD3 and IL-2, melanoma-derived TIL." (PMID 36937426, 2023). "Similarly, A. muciniphila strengthened IL-2 antitumor effects in subcutaneous melanoma and colorectal tumor-bearing mice." (PMID 38045608, 2023). "Thus, the reason why treatment with IL-2 results in a significant decrease in tumor in mouse models but yields a poor result in some patients with melanoma or renal cell cancer is that IL-2 promotes the proliferation of Treg cells." (PMID 37510993, 2023). "It has been shown in a mouse model of melanoma that treatment with anti-CTLA-4 antibody or interleukin 2 (IL-2) immunotherapy leads to persistent production of intratumoral tumor necrosis factor alpha (TNF-α) and T cell accumulation, which increases EZH2 expression." (PMID 37325482, 2023). "Concurrent therapy with immune checkpoint inhibitor plus HD IL-2 has been explored in clinical trials for treatment of melanoma and renal cell carcinoma recently, based on reported synergy between IL-2 based therapy and checkpoint blockade in preclinical models." (PMID 36845705, 2023). "In addition to its exertion in melanoma and renal cell carcinoma, the potential of IL-2 for performing cancer immunotherapy in other solid tumors, such as colorectal and non-small cell lung cancer (NSCLC), was investigated and achieved encouraging outcomes." (PMID 36742134, 2023). "Based on the improved efficacy and safety of systemically administered anti-PD1 compared with IL-2, we hypothesized that the treatment of patients with melanoma LMD with IT anti-PD1 would be safe and feasible." (PMID 36997799, 2023). "It suggests that immunotherapy using IL-2 may have different effects depending on the anatomical site of melanoma, and further studies are needed on this issue." (PMID 36405903, 2022). "Recently, the overexpression of TNF, IFNG and IL2, among other molecules, have been reported as key molecules that may enhance melanoma progression through activating the JAK–STAT signaling pathway." (PMID 36289681, 2022). "Despite these strenuous efforts, only two of these cytokines have been approved by the FDA, IFN-α for the treatment of hairy cell leukemia since 1986 or as adjuvant treatment for melanoma, and IL-2 for the treatment of metastatic renal cancer and advanced melanoma since 1992 and 1998, respectively." (PMID 36497475, 2022). "The local injection of recombinant IL-2 can form rIL-2 depots in melanoma, effectively induce a local immune response, reduce the excessive activation of systemic immune cells, have a highly enhanced therapeutic effect, and significantly reduce the impact of rIL-2 on systemic adverse effects." (PMID 36297527, 2022). "Vaccine regimens incorporating high dose IL-2 as an immune modulator to the melanoma gp100 TAA peptide showed regression of B16 melanoma tumors in mice and increased objective responses in patients with metastatic melanoma as compared to IL-2 or gp100 monotherapy." (PMID 35651800, 2022). "(D) Immunotherapy using interleukin-2 (IL-2) can help a small number of people with stage IV melanoma, and it might be tried if immune checkpoint inhibitors aren’t working." (PMID 36407184, 2022).
melanoma (continued). "Thus, intralesional IL-2 is a drug showing the most benefit in distinct subgroups of melanoma patients and we now provide evidence that this also holds true even after progression on previous immunotherapy." (PMID 35158808, 2022). "We investigated the therapeutic effect of TBI and/or IL-2 treatment in ACT of melanoma." (PMID 36497152, 2022). "Herein, we present the first description of an elderly melanoma patient who developed COVID-19 pneumonia while under treatment with nivolumab and bempegaldesleukin in combination with an investigational PEGylated interleukin (IL-2)." (PMID 35852114, 2022). "Similarly, the inhibition of melanogenesis by D-pen or kojic acid in melanoma cells stimulated the IL-1, IL-2, IL-6, and IL-12 cytokine expression when co-cultured with peripheral blood mononuclear cells." (PMID 35359389, 2022). "Before the era of monoclonal antibodies and molecularly targeted therapy, the mainstay of treatment of advanced inoperable or disseminated malignant melanoma was chemotherapy based mainly on dacarbazine, temozolomide or fotemustine and interleukin 2 immunotherapy." (PMID 35406444, 2022). "High-dose IL-2 therapy is used to expand melanoma TILs in vivo." (PMID 35453572, 2022). "tested whether NBP alendronate plus IL2 suppressed the growth of the melanoma cell line MeWo in NSG mice treated with Vδ2 T cells." (PMID 36275712, 2022). "Whether peripheral eosinophil levels are predictive in therapies other than ICI or IL-2 in melanoma is yet unknown." (PMID 35565423, 2022). "Because NSG mice lack a homeostatic IL2/15R ligand required to support NK-cell survival and expansion, IL2 (50,000 IU/mouse) was injected every other day (intraperitoneally) to support transferred human NK cells and the melanoma burden was monitored by BLI weekly." (PMID 34187852, 2021). "Notably, EZH2 inactivation reversed the drug-resistant phenotype and amplified the effects of anti-CTLA-4 and IL-2 immunotherapy in melanoma mouse models, thus blocking CM growth and dissemination." (PMID 34575678, 2021). "Interestingly, the IT use of immunotherapy dates back to the 1980s, when IT interleukin 2 (IL-2) was first assessed in patients with melanoma LMD." (PMID 35096602, 2021). "Furthermore, IL2-activated NK cells successfully kill melanoma CSCs, which was proven to be a novel method to target melanoma metastasis in the past." (PMID 34202411, 2021). "Another IL-2 variant with decreased binding to high affinity IL-2Rα but increased binding to intermediate affinity IL-2Rβ showed the augmentation of intratumoral CD8/Treg ratio and efficacy in melanoma and colon carcinoma models." (PMID 33803078, 2021). "Here, lymphocytes could be successfully isolated from resected melanomas, followed by in vitro expansion of TILs using IL-2 and confirmation of the specific lysis of autologous tumor cells." (PMID 33807011, 2021). "However, the vast majority of IL-2+ cells also coexpressed high levels of IFN-γ in melanoma specimens." (PMID 34321276, 2021). "However, today, due to severe inflammatory syndromes and limited efficacy in certain cancers (advanced kidney cancer, leukemia, myeloma and melanoma), only IL2 and IFN-α are administered to patients." (PMID 34885023, 2021). "As reviewed, IL-2 is a systemic therapy, but it may also be used as an intralesional therapy for unresectable in-transit melanoma which is refractory to systemic immunotherapy." (PMID 34885172, 2021). "In support of this, in a study in 2001, it was shown that complementary IL-2 expression could remarkably enhance melanoma specific survival of CD8+ T cells in vitro." (PMID 33287413, 2020). "Still, a subset of patients with treatment-refractory disease, late-stage disease, or with recurrent metastases may benefit from intralesional IL2 therapy as suggested by a number of case reports showing complete resolution and remission of advanced melanoma." (PMID 32455916, 2020). "For example, IL2 was shown to directly inhibit the growth of melanoma cells." (PMID 32560387, 2020).
melanoma (continued). "Indeed, several reports have suggested that HD IL-2 therapy provides a high ORR for advanced melanoma, particularly when administered as combination therapy." (PMID 32948031, 2020). "There is a paucity of clinical evidence evaluating the use of intralesional IL2 in melanoma." (PMID 32455916, 2020). "Indeed, a 4–5-fold increase in Tregs was documented in melanoma patients post HD IL-2 therapy, and increased expansion of ICOS+ Tregs correlated with disease progression in these patients." (PMID 32005826, 2020). "For instance, in samples from melanoma patients receiving recombinant IL2 treatment, a signature that could predict the clinical response was identified." (PMID 33049716, 2020). "Furthermore, IFN-α treatment reduced Treg numbers in patients with melanoma and renal cell carcinoma, tentatively attributable to the inhibition of IL-2 production which modulates Treg cell proliferation and activation." (PMID 31900171, 2020). "Interleukin 2 is also effective to treat patients with melanoma when combined with dacarbazine monotherapy or anti-VEGF monoclonal antibody (mAb) monotherapy, but do not increase the effectiveness of neuroblastoma therapy in combination with dinutuximab (anti-GD2 mAb)." (PMID 32582698, 2020). "An advantage of IL-2 therapy is that recombinant human IL-2 is already available in the clinic as a therapeutic drug called Aldesleukin or Proleukin, for the treatment of malignant melanoma and renal cell carcinoma." (PMID 32977677, 2020). "Interestingly, recombinant IL-2 immunotherapy has been shown to be an effective treatment in malignant melanomas and renal cell carcinomas." (PMID 32298379, 2020). "Before immune checkpoint inhibitors (ICIs), BRAF inhibitors and MEK inhibitors became available in the real world, DTIC, type I IFN and/or IL-2-based combined therapies were the main protocol for the treatment of advanced melanoma, although the efficacy of those protocols remained insufficient." (PMID 32948031, 2020). "Thus, low molecular weight polyethyleneimine conjugated with cyclodextrins (CD) and folic acid, to enhance the nanoparticle cellular uptake, have been employed as gene delivery of IL-2 in melanoma cells." (PMID 32225049, 2020). "The first ACT strategies tested with autologous T lymphocytes were based on the isolation of T cells infiltrating primary lesions resected from patients with melanoma (tumor-infiltrating lymphocytes, TILs), followed by their in vitro expansion with high-doses of interleukin-2 (IL-2)." (PMID 33013822, 2020). "This feature may participate to the lower production of IFN-γ and IL-2 by the KO6 clone in response to melanoma lines, which spontaneously express the two main TIGIT ligands, CD155 and CD112, in contrast to T2 cell lines (data not shown)." (PMID 32001504, 2020). "Moreover, in melanoma patients treated with high-dose interleukin-2 or ipilimumab, high VEGF-A serum levels were found to be associated with poor clinical response and decreased overall survival." (PMID 31227006, 2019). "Notably, in vitro activation with high doses of IL-2 reverted the functional defect, as already reported in melanoma patients." (PMID 30911002, 2019). "Based on these results, in 1998, the FDA approved IL-2 for the treatment of unresectable melanoma." (PMID 31028434, 2019). "Adult melanoma patients have been extensively evaluated for adoptive transfer of ex vivo expanded TILs derived from tumor tissue, by culturing single cell suspensions or tumor fragments with high doses of interleukin 2 (IL-2)." (PMID 31398192, 2019). "Myc-KO and Myc-WT NK cells were cultured with B16 melanoma cells for 18 h in the presence of IL2." (PMID 31595191, 2019). "We previously demonstrated that local external beam radiation therapy (RT) and intratumoral (IT) injection of the hu14.18-IL2 immunocytokine (IC), a fusion protein linking hu14.18 anti-GD2 mAb and IL2, achieves improved tumor control and survival in mice bearing B78 melanoma, which expresses GD2." (PMID 31810498, 2019).
melanoma (continued). "In the same year, Lloyd J. Old, Herbert F. Oettgen, and Alexander Knuth demonstrated in the foremost clinical experiments that interleukin-2 (IL-2)-dependent T cells could be trained to recognize and attack malignant melanoma." (PMID 30884760, 2019). "Moreover, IL-2, for instance, has long been approved for the treatment of metastatic renal cell cancer and melanoma." (PMID 31083515, 2019). "IFN-α and IL-2 have been used in the immunotherapy of melanoma for decades." (PMID 31998135, 2019). "More recently, they reported safety and efficacy of HD IL-2 treatment in patients who had previously received anti-PD1 therapy and then progressed, (including both melanoma and mRCC patients) with outcomes similar to patients treated with IL-2 alone as first line therapy." (PMID 30917871, 2019). "IL-2 is a key regulator in supporting proliferation and homeostasis of effector T cells but is also crucial for the development of Treg cells, therefore simultaneously leading to increased numbers of Treg cells in melanoma patients." (PMID 31028434, 2019). "In a comprehensive review of the outcome of 270 patients with unresectable melanoma (8 clinical trials conducted between 1985 and 1993), receiving IL-2 administered at a high dose resulted in a complete response (CR) in 6% and a partial response (PR) in an additional 10% of patients." (PMID 31182961, 2019). "Combining neoadjuvant TMZ (75 mg/m2/day for 14 days) treatment followed by autologous tumor lysate-loaded DC therapy with consecutive IL-2 (3 mIU/day for 5 days) in 17 melanoma patients, also significantly depleted Tregs, although this did not correlate to clinical outcome." (PMID 31020037, 2019). "In addition, MDNA109-Fc demonstrated improved tumor growth inhibition over wild-type IL-2 in the aggressive B16F10 melanoma model." (PMID 30400822, 2018). "Indeed, at the end of the 1980s, it was shown that the TILs in melanoma can be grown in the presence of IL-2 and that they recognize autologous tumor cells." (PMID 29750176, 2018). "However, in the study involving renal cancer and melanoma, subjects which were given high dose of IL-2 showed limited efficacy due to increased Treg level." (PMID 29854806, 2018). "Low-dose cyclophosphamide and low-dose interleukin-2 for malignant melanoma." (PMID 30400822, 2018). "NHS-IL2 combined with SBRT had acceptable safety and tolerability, and demonstrated disease control in heavily pretreated patients with advanced melanoma who failed ipilimumab +/- anti-PD1 without the toxicities often associated with IL-2 treatment." (PMID 30400835, 2018). "Ninety one patients receiving IL2 therapy for metastatic renal cell carcinoma and melanoma at Huntsman Cancer institute (HCI), Utah from May 2009 to October 2016 were retrospectively evaluated for rigor prophylaxis." (PMID 30342473, 2018). "Also, intra-tumoral administration of adenoviruses encoding IL-2 and TNF-α into B16 melanoma tumors showed anti-tumor activity in comparison to T-cell or control viral transfer alone." (PMID 29588627, 2018). "The previously reported coincidence of PH and IL2 therapy in melanoma patients indicate that there might be a pathogenically link between PH and combined immunotherapy in the present case as well." (PMID 30376886, 2018). "Moreover, different phase I and II studies investigating the combination of IL-2 and RT in renal cell carcinoma, melanoma and non-small cell lung cancer are ongoing (NCT01884961, NCT02306954, NCT030226236, NCT03224871)." (PMID 30619273, 2018). "In this open-label phase 2 trial we sequenced the BRAF inhibitor vemurafenib with HD IL-2 in the treatment of patients with stage IV, metastatic BRAF-mutated malignant melanoma and assessed the toxicity and efficacy specifically with regard to the complete response rate from this combination." (PMID 30053905, 2018). "We found that the intrinsic ability of Teff to inhibit melanoma may also be enhanced by local production of IL-2 by Tmem." (PMID 29843822, 2018).